SPICE1 (spindle and centriole associated protein 1)
Description:
Regulator required for centriole duplication, for proper bipolar spindle formation and chromosome congression in mitosis.
Synonyms: CCDC52; SPICE
Tractability: Antibody: its Gene Ontology location is reachable by antibodies, with high confidence. PROTAC: ubiquitination databases record sites on it.
Gene: Protein-coding gene on chromosome 3 (113,442,718 to 113,515,606, reverse strand). Ensembl gene ENSG00000163611.
Subcellular location: Cytoplasm, cytoskeleton, microtubule organizing center, centrosome; Cytoplasm, cytoskeleton, microtubule organizing center, centrosome, centriole; Cytoplasm, cytoskeleton, spindle
Subcellular location (Human Protein Atlas): Basal body; Centrosome
Gene Ontology:
Molecular function: protein binding
Biological process: metaphase chromosome alignment; mitotic spindle assembly; regulation of centriole replication
Cellular component: centriole; centrosome; ciliary basal body; spindle
Genetic constraint (gnomAD): Loss-of-function variants: 63 observed, 86.85 expected, observed/expected ratio (o/e) 0.73, 90% interval 0.59 to 0.89. The upper end of that interval is the gene's LOEUF score, 0.89, which puts it in group 3 of 6, group 1 being the genes least tolerant of losing a copy. Missense variants: 908 observed, 989.85 expected, observed/expected ratio (o/e) 0.92, 90% interval 0.87 to 0.97. Synonymous variants: 291 observed, 344.99 expected, observed/expected ratio (o/e) 0.84, 90% interval 0.77 to 0.93.
Homologues: Orthologues: chimpanzee SPICE1 (99% identical), macaque SPICE1 (95% identical), rabbit SPICE1 (84% identical), pig SPICE1 (83% identical), dog SPICE1 (82% identical), mouse Spice1 (77% identical), rat Spice1 (76% identical), guinea pig SPICE1 (68% identical), tropical clawed frog spice1 (32% identical), zebrafish spice1 (26% identical).
Diseases named in the same sentence as SPICE1 in open-access papers:
SPICE1 is named in the same sentence as 7 diseases in open-access papers, as found by Europe PMC text mining. Sharing a sentence is not in itself a finding about the gene and the disease. The quoted sentences say what the papers report.
osteosarcoma (1 paper, 2026). A usually aggressive malignant bone-forming mesenchymal neoplasm, predominantly affecting adolescents and young adults. "As for metabolic reprogramming, SPICE1 facilitates osteosarcoma progression by enhancing USP10-mediated deubiquitination and stabilization of FASN, thereby fueling lipid biosynthesis and tumor growth." (PMID 41522354, 2026).
tumor (3 papers, 2018 to 2026). "Using TOST we identified two equivalently changed genes (SPICE1 and MCEMP1) and one inverse changed gene (STAMBPL1) by comparing tumor tissue data set 1 with the PBMC data set." (PMID 36304274, 2022).
SPICE1 also shares sentences with these, for which no sentence is quoted: epilepsy (1 paper); Granuloma (1); lung carcinoma (1); neurodevelopmental disorder (1); sarcoidosis (1).